CDK4 (cyclin dependent kinase 4)
Diseases named in the same sentence as CDK4 in open-access papers (continued):
Sharing a sentence is not in itself a finding about the gene and the disease.
breast cancer (continued). "Several studies have shown that endocrine resistance mechanisms depend on alterations of cell cycle regulators, which led to the development of cyclin-dependent kinases 4 and 6 inhibitors (CDK4/6i) for ER+ advanced breast cancer." (PMID 39931212, 2024). "Because CDK4/6 inhibitors have already been developed and effectively used to treat breast cancer tumors, clinicians are testing the efficacy of CDK4/6 inhibitors in combination with other inhibitors to combat melanoma." (PMID 38732242, 2024). "One study utilising CDK4/6 inhibitor on ER+/HER2− breast cancer patients and another study utilising kinase inhibitor on ER+/HER2+ patients showed pCR rate of 5% (n=1) and 0% (n=1), respectively." (PMID 38576013, 2024). "Several studies, including NeoPalAna24, neoMONARCH25, and FELINE26, supported the efficacy of different CDK4/6 inhibitors combined with ET for achieving CCCA in various subsets of breast cancer patients." (PMID 38448600, 2024). "Currently, there are ongoing preclinical and clinical trials investigating the combination of CDK4/6i with immune checkpoint blockade (ICB) therapy for breast cancer." (PMID 38409585, 2024). "This study not only unveils the mechanism governing resistance to CDK4/6i but also offers a potential avenue for the future treatment of palbociclib-resistant breast cancer patients." (PMID 38961064, 2024). "Collectively, our studies shed light on the mechanism regulating palbociclib resistance and present clinical evidence for developing therapeutic approaches to treat CDK4/6i-resistant breast cancer patients." (PMID 38961064, 2024). "At present, the Food and Drug Administration (FDA) has sanctioned various CDK4/6i for employment as the primary treatment regimen in HR + /HER2- breast cancer." (PMID 38409585, 2024). "This network meta-analysis aimed to systematically evaluate the efficacy and safety of CDK4/6 inhibitors combined with ET for HR+/HER2-breast cancer." (PMID 38832268, 2024). "We also describe the effects of INX-315 in preclinical models of CCNE1-amplified cancer and use the compound to dissect out the roles of CDK2 and CDK4/6 in treatment-naïve and therapy-resistant luminal breast cancers." (PMID 38047585, 2024). "To date, the U.S. Food and Drug Administration (FDA) has approved three selective CDK inhibitors (palbociclib, ribociclib, and abemaciclib) for breast cancer, and 15 CDK4/6 inhibitors are in clinical trials." (PMID 38589831, 2024). "CDK4/6 inhibitors have emerged as a cornerstone in the treatment of HR-positive metastatic breast cancer over this decade." (PMID 39133334, 2024). "A better understanding of the intricate molecular pathways involved in the sensitivity and the resistance to CDK4/6i will pave the way for a more tailored and personalised treatment of breast cancer patients." (PMID 39090361, 2024). "OP-1250 works well in combination with cyclin-dependent kinase 4 and 6 inhibitors in preclinical studies, leading to significant tumor shrinkage in intracranial breast cancer models and extending the lifespan of the test subjects." (PMID 38800404, 2024). "For example, the addition of CDK4/6 inhibitors to hormone deprivation therapy in HR + breast cancer, exploiting the CDK4/6 dependency of HR + breast cancer under hormone deprivation, is now the first-line treatment for advanced HR + breast cancer." (PMID 39501277, 2024). "While CDK4/6 inhibitors have revolutionized HR + breast cancer therapy, there is limited understanding of their efficacy in TNBC and meaningful predictors of response and resistance to these drugs remain scarce." (PMID 38831405, 2024). "So far, combining a CDK4/6 inhibitor (CDK4/6i) with endocrine therapy (ET) has emerged as the established treatment approach for this form of breast cancer." (PMID 38166784, 2024).
breast cancer (continued). "The efficacy of CDK4/6 inhibitors in the treatment of HR+/HER2- breast cancer demonstrates the success of applying basic knowledge of cell cycle regulation to the generation of clinically-relevant drugs." (PMID 38562687, 2024). "Background/Objectives: Dose reductions in CDK4/6 inhibitors, such as ribociclib and palbociclib, are often necessary due to treatment-related toxicities in patients with advanced breast cancer." (PMID 39727671, 2024). "In hematopoietic malignancies, breast cancer, and melanoma, CDK4 and 6 are considered attractive therapeutic targets." (PMID 39598723, 2024). "We show that RET is upregulated in ER+ breast cancer cell lines resistant to combined CDK4/6i and fulvestrant compared to isogenic cells resistant to fulvestrant alone." (PMID 39931212, 2024). "The addition of CDK4/6 inhibitors in HR+/HER2- early breast cancer patients significantly improved IDFS in adjuvant therapy and CCCA in neoadjuvant." (PMID 39329126, 2024). "The complete clinicopathological features of 152 patients with advanced ER-high HER2-negative breast cancer receiving CDK4/6 inhibitor combined with endocrine as first-line therapy were collected in this study." (PMID 39020297, 2024). "Our clinical studies contribute crucial evidence to support the proposition that MITF is pivotal in orchestrating resistance to CDK4/6i among breast cancer patients." (PMID 38961064, 2024). "It has been reported that the combined use of CDK4/6 inhibitors and mTOR inhibitors can provide greater benefits to patients in the treatment of breast cancer." (PMID 38890443, 2024). "Palbociclib was the first CDK4/6 inhibitor to be approved by the FDA for breast cancer in combination with AIs in 2015." (PMID 38255807, 2024). "Numerous preclinical studies have demonstrated that luminal breast cancer exhibits overactivity in the CDK4/6-cyclin D1 pathway, which provides a strong rationale for the therapeutic efficacy of CDK4/6 inhibitors." (PMID 39329126, 2024). "The MONALEESA-3 study (51% of endocrine-sensitive population) recommends Fulvestrant as another partner for CDK4/6i in the treatment of HR + /HER2- advanced breast cancer." (PMID 38409585, 2024). "Recently, data from male breast cancer patients included in ribociclib and abemaciclib trials supported expanding approval of the CDK4/6i to include men." (PMID 37903899, 2024). "The dependence of breast cancer on CDK4/6 and its binding partner cyclin D1 for progression through the G1/S phase of the cell cycle has made breast cancer a prime target for the implementation of CDK4/6 inhibitor-based therapy." (PMID 38730702, 2024). "We supplemented our proteomics investigation with analyses of RNA-seq data (GSE99116) obtained from a recent study where different CDK4/6 inhibitors were compared for transcriptional changes in breast cancer cell lines." (PMID 38927958, 2024). "Palbociclib is a CDK4/6 inhibitor approved for the treatment of breast cancer by suppressing cell proliferation." (PMID 39362848, 2024). "Overall, our data suggest that DNA‐damaging agents and CDK4/6i induce senescence in breast cancer cells to a similar extent." (PMID 37854019, 2024). "Herein, we present a retrospective analysis of breast cancer patients treated at our institution with the CDK4/6i combined with SABR." (PMID 39120877, 2024). "The combination of PI3K inhibitors and CDK4/6 inhibitors in HR+ breast cancer is driven by their complementary mechanisms." (PMID 38172946, 2024). "This study revealed poor efficacy for CDK4/6 inhibitor combined with endocrine therapy for HR+/HER2-low breast cancer in vitro and in vivo models." (PMID 39730704, 2024). "Given the clinical relevance of TIS in cancer treatment, we focused our study on the CDK4/6 inhibitor palbociclib, which is approved for the treatment of breast cancer and is under intense investigation for additional malignancies." (PMID 38693312, 2024).
breast cancer (continued). "In this study, we aimed to assess the role of baseline PET-CT assessment in patients with advanced breast cancer who received CDK4/6 inhibitors in second-line setting." (PMID 39697231, 2024). "Our study provides the RWE data with the use of CDK4/6 inhibitors in the treatment of metastatic HR+/HER2− breast cancer." (PMID 39338149, 2024). "[18F]CDKi, a modified palbociclib, was the only PET tracer that successfully delineated CDK4/6 in the MCF-7 breast cancer model." (PMID 38999983, 2024). "The overall results demonstrate that imlunestrant has an adaptable safety profile with antitumor activity in ER+/HER2− advanced breast cancer, including in patients with baseline ESR1 mutations and fulvestrant- and/or CDK4/6 inhibitor-refractory disease." (PMID 39767607, 2024). "The findings support further investigation of this regimen for PIK3CA-mutant HR+ breast cancer patients who show resistance to ET and CDK4/6i or cross-resistance to PI3Kα inhibitors." (PMID 39409880, 2024). "Nearly 70% of HR+/HER2-low breast cancer patients in the DESTINY-Breast 04 study had previously received CDK4/6i treatment." (PMID 39267829, 2024). "The specific CDK7 inhibitors are predominantly assessed in patients with locally advanced or metastatic HR+/HER2- breast cancer, who exhibited failure in prior treatment with a CDK4/6 inhibitor in combination with hormonal therapy." (PMID 38605321, 2024). "FGFR multi-TKI lucitanib has shown promising activity in overcoming that resistance; thus, there is potential for the combination use of CDK4/6 inhibitors with FGFR inhibitors in breast cancers with FGFR pathway alterations." (PMID 38255923, 2024). "Research has shown that HER2 significantly boosts CDK4/6 activity through phosphorylated Rb (pRb) in HER2+ breast cancer, suggesting the potential responsiveness of HER2+ breast cancer to CDK4/6i." (PMID 38409585, 2024). "The PALOMA-3, MONALEESA-3, and MONARCH-2 trials investigated the suitability of CDK4/6i as a treatment option for patients with endocrine-resistant breast cancer and BM." (PMID 38409585, 2024). "The effect of palbociclib on cell cycle progression was maintained for at least 2 weeks, contrary to the rapidly developing resistance to CDK4/6 inhibition described in breast cancer cells." (PMID 36453028, 2024). "Our findings confirm that adding CDK4/6 inhibitors to the regimen of treatment-naïve HR + patients with advanced breast cancer significantly improves survival." (PMID 39161906, 2024). "Zhao and Burgess reported the first CDK4/6 PROTAC compound based on cereblon recruiter (pomalidomide) that was active against the MDA-MB-231 breast cancer cell line in the nanomolar range and reduced the pRB level." (PMID 39598723, 2024). "Data regarding the efficacy and characteristics of chemotherapy following CDK4/6 inhibitors in luminal breast cancer in both clinical trials and real-world data (RWD) are limited." (PMID 39199665, 2024). "In breast cancer, the complexes of cyclin D–cyclin-dependent kinase 4 (cyclin D–cdk4) and cyclin E–cdk2 catalyze hyperphosphorylation, inactivate RB." (PMID 38542956, 2024). "To validate our model of therapy-induced senescence (TIS), we firstly quantified the cytostatic effect of the CDK4/6 inhibitor palbociclib by analyzing the cell cycle of human breast cancer cells following palbociclib treatment." (PMID 38693312, 2024). "Despite several alternative treatment modalities, such as CDK4/6-inhibitors (introduced in 2017 in Danish practice), having surfaced over the years for ER-positive advanced breast cancer patients, there is still a use of capecitabine as first-line therapy." (PMID 38912829, 2024).
breast cancer (continued). "Current guidelines recommend CDK4/6 inhibitors as either first-line or second-line treatment for patients with advanced breast cancer." (PMID 39697231, 2024). "Earlier studies in breast cancer have shown that CDK4/6-inhibitor-treated cells depict early adaptive responses and quickly evade cytostasis by amplifying the cyclin D1-CDK2 axis." (PMID 39123441, 2024). "The treatment paradigm for HR+ and HER2- breast cancer has undergone a significant shift with the discovery of CDK4/6 inhibitors." (PMID 38344632, 2024). "Significantly, even at lower doses, neratinib amplified the therapeutic potential of CDK4/6 inhibitor combined with endocrine therapy in HR+/HER2-low breast cancer." (PMID 39730704, 2024). "This trial suggested a resensitizing effect of CDK4/6 inhibitors in HER2-resistant breast cancer, providing valuable insights into potential combination therapies." (PMID 39093344, 2024). "We found that YAP activity is dependent on MAP3K3 in CDK4/6 inhibitor-resistant breast cancer cells and BRAF inhibitor-resistant melanoma cells." (PMID 38622197, 2024). "Previous reports have demonstrated the variable responsiveness of HR+/HER2-low breast cancer to the combination of CDK4/6 inhibitors with endocrine therapy." (PMID 39730704, 2024). "Double suppression of CDK4/6 and ER signals, known as palbociclib with an AI, can control the cell cycle and block the proliferation of breast cancer cells, so it is the first-line choice in postmenopausal females." (PMID 38255807, 2024). "Second, we have found that although CDK4/6i monotherapy is sufficient to induce complete cell cycle arrest in breast cancer cells, their combination with CDK2 inhibitors upfront significantly delays the development of acquired resistance." (PMID 38047585, 2024). "Patients and methods: This retrospective multicenter study included elderly patients with metastatic HR+/HER2-negative breast cancer receiving first-line CDK4/6 inhibitors." (PMID 39456537, 2024). "They concluded that TWIST1 upregulation is a potential target for reversing resistance to the CDK4/6 inhibitor in metastatic luminal breast cancer cells." (PMID 38540112, 2024). "Our preclinical studies demonstrate activity for INX-315 in both CCNE1-amplified cancers and CDK4/6i–resistant breast cancer." (PMID 38047585, 2024). "BZA reduces high-risk biomarkers and provides clinical benefit for hormone receptor (HR)+/HER2- breast cancer patients when combined with CDK4/6 inhibitor palbociclib (NCT02729701, NCT02448771)." (PMID 39768178, 2024). "There has been increased interest in CDK4/6 inhibitors as potential therapeutic approaches for neoadjuvant and adjuvant therapy for early breast cancer." (PMID 39329126, 2024). "Dr. Slamon is also a leader in the development of CDK4/6 inhibitors for breast cancer therapy, which paves the way for new strategies to treat this devastating disease." (PMID 38894873, 2024). "The CDK2 inhibitor INX-315 induces cell cycle arrest and therapy-induced senescence, thereby controlling the growth of CCNE1-amplified cancers and CDK4/6 inhibitor-resistant breast cancers, which together supports future clinical development." (PMID 38047585, 2024). "With regards to abemaciclib, to our knowledge, there are only two studies that addressed its cost-effectiveness compared to other CDK4/6 inhibitors in advanced breast cancer, and both were carried out in the US." (PMID 39114308, 2024). "We also investigated the COL11A1 effect on the responsiveness of the cells to CDK4/6 inhibitors including palbociclib, abemaciclib and ribociclib, which are now frequently used in treating ER+ breast cancer patients." (PMID 38806505, 2024). "From 2015 to 2022, 24 eligible patients were treated with CDK4/6 inhibitors for metastatic estrogen receptor-positive (ER+)/HER2- breast cancer." (PMID 38344632, 2024). "Efficient CDK4/6 inhibitors such as Palbocilicb, Ribociclib, and Abemaciclib are currently in clinical use against breast cancer." (PMID 39088265, 2024).
breast cancer (continued). "In patients with breast cancer with bone metastases, CDK4/6 inhibitors and osteoclast inhibitors are concomitantly used for their respective indications." (PMID 38248101, 2024). "In Qatar, there is only one cost-effectiveness study that was carried out regarding the use of CDK4/6 inhibitors in HR+/HER2- advanced breast cancer patients." (PMID 39114308, 2024). "For patients with hormone receptor-positive, HER2-negative (HR+/HER2−) advanced breast cancer, the combination of cyclin-dependent kinase 4/6 inhibitors (CDK4/6i) with endocrine therapies has revolutionized treatment." (PMID 39766060, 2024). "Recent applications of CDK4/6i in neoadjuvant therapy for breast cancer are the subject of ongoing clinical trials." (PMID 38409585, 2024). "CDK2, a critical regulator of the cell cycle, is a promising drug target, especially in cancers with cyclin E1 protein overexpression, including HR+/HER2− breast cancer resistant to CDK4/6 inhibitors." (PMID 39184861, 2024). "The addition of locoregional radiotherapy to first-line CDK4/6 inhibitors warrants further investigation across various clinical scenarios in advanced breast cancer." (PMID 39065777, 2024). "The efficacy of different combinations of CDK4/6 inhibitors in the treatment of breast cancer was not only validated by trials, but also confirmed by meta-analysis." (PMID 39161906, 2024). "Neoadjuvant endocrine therapy has traditionally been limited to a minority of patients; nevertheless, interest in the activity of CDK4/6 inhibitors in early breast cancer prompted the initiation of four RCTs." (PMID 39329126, 2024). "Studies in breast cancer models have shown that combining CDK4/6 and PI3K inhibitors can prevent resistance to PI3K inhibitors while also stopping cancer cells from adapting to CDK4/6 inhibitors." (PMID 39769028, 2024). "Drugs like palbociclib, ribociclib, and abemaciclib are examples of CDK4/6 inhibitors approved for certain types of breast cancer." (PMID 38730642, 2024). "In advanced HR+ breast cancer, the combination of endocrine therapy with cyclin-dependent kinase 4/6 (CDK4/6) inhibitors is considered the standard of care in the front-line setting." (PMID 38791880, 2024). "Intrinsic and acquired resistances to CDK4/6 inhibitors have been described in patients with breast cancer." (PMID 38503755, 2024). "In breast cancer models, cells activate autophagy in response to Palbociclib, and a blockade of autophagy significantly improved the efficacy of CDK4/6 inhibition in in vitro and in vivo breast cancer models with an intact G1/S transition." (PMID 38338777, 2024). "This impact was correlated with a notable decrease in the mRNA levels of cyclin D1 and cyclin-dependent kinase (CDK4) in both breast cancer cell lines." (PMID 38563878, 2024). "In this study, we aim to explore the prognostic and predictive potential of large unstained cells in the context of metastatic HR+ HER2-negative breast cancer, focusing specifically on patients undergoing treatment with CDK4/6 inhibitors." (PMID 39797256, 2024). "FGFR1 amplification and overexpression also contribute to the resistance of breast cancer cells to the CDK4/6 inhibitors used in combination with endocrine therapy in either in vitro or in vivo patient-derived xenograft models." (PMID 38255923, 2024). "Recent studies have indicated that the effectiveness of CDK4/6 inhibitors is challenged due to acquired resistance in breast cancer patients." (PMID 39123441, 2024). "Inhibition of the NFKB (NRF) TF along with non-coding the RNA TROJAN has been shown to abolish CDK2 activity and reverse the resistances of breast cancer cells to CDK4/6 inhibitors." (PMID 39376611, 2024). "By specifically inhibiting the cyclin D-CDK4/6-Rb pathway, CDK4/6 inhibitors overcome endocrine resistance in HR+ breast cancer, which successfully delays the progression of the disease." (PMID 38240835, 2024).